ERCC2 (ERCC excision repair 2, TFIIH core complex helicase subunit)
Diseases named in the same sentence as ERCC2 in open-access papers (continued):
Sharing a sentence is not in itself a finding about the gene and the disease.
gastric cancer (14 papers, 2008 to 2025). A primary or metastatic malignant neoplasm involving the stomach. "Eleven studies including 2898 gastric cancer patients reported an association between ERCC2 rs13181 and rs1799793 polymorphisms and the clinical response to platinum-based chemotherapy." (PMID 30581498, 2018). "Nevertheless, this meta-analysis suggests that the ERCC2 rs1799793 polymorphism is a predictor of prognosis in Asian gastric cancer patients undergoing platinum-based chemotherapy." (PMID 30581498, 2018). "Several researchers have reported a relationship between ERCC2 rs13181 and rs1799793 polymorphisms and chemotherapy efficacy in gastric cancer patients." (PMID 30581498, 2018). "Thirteen studies including 3096 gastric cancer patients identified the association between ERCC2 rs13181 or rs1799793 polymorphisms and clinical response to platinum-based chemotherapy drugs." (PMID 30581498, 2018). "Ten studies including 2675 gastric cancer patients were identified for the association between the ERCC2 rs1799793 polymorphism and OS." (PMID 30581498, 2018). "Ten studies including 2502 gastric cancer patients revealed an association between the ERCC2 rs13181 polymorphism and OS." (PMID 30581498, 2018). "Polymorphisms in ERCC2 are closely related to the efficacy of chemotherapy drugs in gastric cancer patients." (PMID 30581498, 2018). "In the group with gastric cancer, the ERCC2 polymorphism was confirmed to increase the risk of cancer in the homozygote comparison and the recessive model, but not in the heterozygote comparison and the dominant model." (PMID 28489582, 2017). "The present study also revealed that ERCC2 rs1799793 is an important factor influencing the response to chemotherapy and OS in cases of gastric cancer, following adjustment for multiple potential risk factors." (PMID 26622786, 2015). "For ERCC2 rs1799793, the GA+AA genotypes were found to be significantly associated with a lower risk of mortality from gastric cancer compared with that of the GG genotype (HR, 1.97; 95% CI, 1.28–3.03; P=0.001)." (PMID 26622786, 2015). "The genotypes of ERCC1 rs11615 and ERCC2 rs1799793 were revealed to affect the response to chemotherapy, and were associated with the OS in gastric cancer patients." (PMID 26622786, 2015). "In the present study, we assessed associations of ERCC1 (rs3213986) and ERCC2 (rs13181, and rs1799793) SNPs with survival in gastric cancer patients." (PMID 24023723, 2013). "Stratification analysis for associations between ERCC1 and ERCC2 SNPs and overall survival in gastric cancer patients." (PMID 24023723, 2013). "Univariate and multivariate analyses of associations between ERCC1 and ERCC2 haplotypes and overall survival in gastric cancer patients." (PMID 24023723, 2013). "Univariate and multivariate analyses of associations between ERCC1 genotype, ERCC2 genotypes, combined ERCC1 and ERCC2 variants and overall survival in gastric cancer patients." (PMID 24023723, 2013). "The present study showed that the ERCC2 rs1799793 AA genotype was associated with OS in gastric cancer patients." (PMID 24023723, 2013). "This meta-analysis suggested that the ERCC2 rs1799793 polymorphism might be a predictor of prognosis in gastric cancer patients subjected to platinum-based chemotherapy." (PMID 30581498, 2018). "Furthermore, two previous studies reported an association between ERCC2 rs1799793 and survival in gastric cancer patients." (PMID 26622786, 2015). "We genotyped by the TaqMan assay three common, potentially functional ERCC1 (rs3212986) and ERCC2 SNPs (rs13181 and rs1799793) in 360 gastric cancer patients." (PMID 24023723, 2013). "False-positive report probability for Association between overall survival in gastric cancer patients and the genotypes and haplotypes of ERCC1 and ERCC2 variants." (PMID 24023723, 2013).
gastric cancer (continued). "Nevertheless, some greater FPRP values (>0.2) were observed for some other significant associations in stratified analyses (e.g. ERCC2 rs13181 and ERCC1 rs3213986 variant genotypes with gastric cancer OS)." (PMID 24023723, 2013). "First, we were unable to explore the exact mechanism by which ERCC1 and ERCC2 SNPs influence gastric cancer survival." (PMID 24023723, 2013). "Nevertheless, there have been implications that SBS5 may be contaminated with SBS16 with unknown origin, so further refinements are necessary to confirm the exact aetiology of SBS5 and to evaluate its potential relation to ERCC2 in gastric cancer." (PMID 37568604, 2023). "In addition, neither of the two studies were focused on the relationship between ERCC2 rs1799793 and the clinical response of gastric cancer patients to platinum-based chemotherapy." (PMID 30581498, 2018). "For these reasons, whether there are connections between ERCC2 and the clinical outcomes of gastric cancer patients in response to platinum-based chemotherapy is a hot question." (PMID 30581498, 2018). "In conclusion, the results of the present study suggest that the ERCC1 rs11615 and ERCC2 rs1799793 SNPs in DNA repair pathways may be utilized as predictive factors of the clinical outcome in gastric cancer patients." (PMID 26622786, 2015). "In conclusion, these results suggest that ERCC1 rs11615 and ERCC2 rs1799793 in the DNA repair pathways may be used as predictive factors of the clinical outcome in gastric cancer patients." (PMID 26622786, 2015). "Considering these data, ERCC2 SNPs may serve as predictors of chemotherapy response in gastric cancer patients." (PMID 26622786, 2015). "For example, only a small study showed that ERCC2 Lys751Gln (rs13181) SNP might be a predictive maker for outcomes in Hispanic patients with stage III/IV gastric cancer." (PMID 24023723, 2013). "However, few studies have simultaneously investigated the roles of ERCC1 and ERCC2 SNPs in clinical outcomes in gastric cancer patients." (PMID 24023723, 2013). "In summary, we found that ERCC1 and ERCC2 functional SNPs may independently (rs1799793) and jointly (rs1799793, rs13181 and rs3212986) affect the OS in North American gastric cancer patients." (PMID 24023723, 2013). "In the present study, we investigated whether functional ERCC1 rs3213986 G>T and ERCC2 rs13181 T>G and rs1799793 G>A SNPs have any individual or joint effects on clinical outcomes of gastric cancer patients in a North American patient population." (PMID 24023723, 2013). "ERCC2 rs50871 G/T, ERCC6 rs1917799 G/T and DDB2 rs3781619 A/G polymorphisms were significantly associated with shorter OS, while ERCC1 rs3212961 A/C, ERCC5 rs2094258 A/G and DDB2 rs830083 C/G could predict favorable OS of gastric cancer patients." (PMID 35955506, 2022). "Thus, ERCC2 rs1799793 may be a useful biomarker in predicting the clinical outcomes of gastric cancer patients in response to platinum-based chemotherapy." (PMID 30581498, 2018). "And the ERCC2 rs1799793 polymorphism, together with ERCC1 rs11615 polymorphism, may play roles in the response to chemotherapy and overall survival for patients with gastric cancer." (PMID 28388903, 2017). "ERCC1 and ERCC2 functional SNPs may jointly affect OS in Caucasian gastric cancer patients." (PMID 24023723, 2013). "Furthermore, ERCC2 rs13181 and rs1799793 SNPs have been shown to be prognostic predictors for patients with osteosarcoma, colorectal cancer, and oral cancer, but to date, few studies have investigated prognostic importance of these SNPs in gastric cancer patients." (PMID 24023723, 2013).
osteosarcoma (14 papers, 2011 to 2025). A usually aggressive malignant bone-forming mesenchymal neoplasm, predominantly affecting adolescents and young adults. "In one germline study performed on 130 patients with osteosarcoma treated with neoadjuvant cisplatin-based therapy in combination with doxorubicin, methotrexate, and ifosfamide the ERCC2 rs13181 and ERCC2 rs1799793 SNPs were associated with survival." (PMID 36233089, 2022). "Seven studies 10–16 for the relationship between ERCC2 rs13181 (Lys751Gln) gene polymorphism and overall survival of osteosarcoma were included in this meta-analysis." (PMID 34394247, 2020). "Two studies 7,8 for the relationship between ERCC2 rs1799793 (A>G) gene polymorphism and osteosarcoma risk were included in this meta-analysis." (PMID 34394247, 2020). "Three studies 7–9 for the relationship between ERCC2 rs13181 (Lys751Gln) gene polymorphism and osteosarcoma risk were included in this meta-analysis." (PMID 34394247, 2020). "Seven studies 9–12, 14–16 for the relationship between ERCC2 rs1799793 (Asp312Asn) gene polymorphism and overall survival of osteosarcoma were included in this meta-analysis." (PMID 34394247, 2020). "ERCC1 (C118T (rs11615) and C8092A (rs3212986)) and ERCC2 (A751C (rs171140) and G312A (rs1799793)) polymorphisms were analysed in 44 patients with osteosarcoma, who were treated with cisplatin based neoadjuvant chemotherapy." (PMID 29980176, 2018). "Our meta-analysis included eleven studies in which four SNPs (ERCC1 rs11615 and rs3212986, ERCC2 rs13181 and rs1799793) reportedly associated with osteosarcoma prognosis were investigated." (PMID 28977987, 2017). "To investigate correlations between excision repair cross-complementation group 1 (ERCC1) and 2 (ERCC2) polymorphisms and osteosarcoma prognosis, we conducted a meta-analysis of studies published through October 2016." (PMID 28977987, 2017). "We found that GA+AA genotype of ERCC2 rs1799793 or GC+CC genotype of NBN rs1805794 were associated with an increased risk of osteosarcoma in females, with ORs(95%CI) of 2.42(1.20-4.87) and 2.01(1.07-4.23), respectively." (PMID 26101473, 2015). "We found that GA+AA genotype of ERCC2 rs1799793 or GC+CC genotype of NBN rs1805794 were associated with an increased risk of osteosarcoma in females, and the ORs(95%CI) were 2.42(1.20-4.87) and 2.01(1.07-4.23), respectively." (PMID 26101473, 2015). "Conditional logistic regression analyses found that individuals carrying with GA+AA genotype of ERCC2 rs1799793 were significantly associated with increased risk of osteosarcoma when compared with GG genotype (OR=1.58, 95%CI=1.03-2.41)." (PMID 26101473, 2015). "ERCC2 rs13181 A allele and GG genotype were associated with overall survival of osteosarcoma." (PMID 34394247, 2020). "In conclusion, our study is, to our knowledge, the first to examine prospectively an increased risk role of ten SNPs in DNA repair pathway in osteosarcoma susceptibility, and we found that ERCC2 rs1799793 and NBN rs1805794 polymorphisms modulate the risk of developing osteosarcoma." (PMID 26101473, 2015). "Several ERCC single nucleotide polymorphisms (SNPs) associated with osteosarcoma prognosis have been reported, including ERCC1 rs11615 (Asn118Asn) and rs3212986 (Gln504Lys), and ERCC2 rs13181 (Lys751Gln) and rs1799793 (Asp312Asn)." (PMID 28977987, 2017). "There existed controversies about the association between the response to chemotherapy for osteosarcoma (OS) patients and the genetic polymorphisms in excision repair cross-complementation group (ERCC1 and ERCC2) genes." (PMID 28388903, 2017). "First of all, although this study suggested that ERCC2 rs1799793 and NBN rs1805794 polymorphisms were associated with osteosarcoma risk, more biological background data are needed to explain our results." (PMID 26101473, 2015). "In our meta-analysis, we found that ERCC2 rs13181 A allele and GG genotype were associated with overall survival of osteosarcoma, but AA genotype not." (PMID 34394247, 2020).
osteosarcoma (continued). "Our results suggest that ERCC2 rs1799793 and NBN rs1805794 polymorphisms were associated with an increased risk for osteosarcoma, which suggests that NER and HRR pathways modulate the risk of developing osteosarcoma." (PMID 26101473, 2015). "Moreover, we conducted stratification analysis on the association between ERCC2 rs1799793 and NBN rs1805794 and demographic characteristics in osteosarcoma patients." (PMID 26101473, 2015). "Conditional logistic regression analyses found that individuals carrying with GA+AA genotype of ERCC2 rs1799793 and GC+CC genotype of NBN rs1805794 were significantly associated with increased risk of osteosarcoma, and the ORs(95%CI) were 1.58(1.03-2.41) and 2.66(1.73-4.08), respectively." (PMID 26101473, 2015). "We also found that ERCC2 rs1799793 and NBN rs1805794 may be associated with carcinogenesis of osteosarcoma." (PMID 26101473, 2015). "A deficiency in the ability to repair DNA damages could therefore alter the response to treatment with a significant positive association between the polymorphism ERCC2 gene, Lys751Gln, but also ERCC1, Asn118Asn with the improved cisplatin response in osteosarcoma." (PMID 35955506, 2022). "A deficiency in the ability to repair DNA damages could therefore alter the response to treatment with a significant positive association between polymorphism ERCC2 gene, Lys751Gln, but also ERCC1, Asn118Asn with the improved cisplatin response in osteosarcoma." (PMID 35955506, 2022). "Interestingly, ERCC2 rs13181 A allele and GG genotype were associated with overall survival of osteosarcoma, but AA genotype not." (PMID 34394247, 2020). "Interestingly, ERCC2 rs13181 A allele and GG genotype were associated with overall survival of osteosarcoma, but AA genotype not (A allele: OR = 0.78, 95% CI: 0.65–0.93, P = 0.007; GG genotype: OR = 1.32, 95% CI: 1.05–1.65, P = 0.02; AA genotype: OR = 0.69, 95% CI: 0.45–1.04, P = 0.08)." (PMID 34394247, 2020).
Xeroderma pigmentosum complementation group D (12 papers, 2006 to 2025). Xeroderma pigmentosum complementation group D (XPD) is a subtype of xeroderma pigmentosum (XP; see this term), a rare photodermatosis predisposing to skin cancers. "ERCC2, also called xeroderma pigmentosum complementation group D (XPD), encodes a protein involved in transcription-coupled nucleotide excision repair." (PMID 21496236, 2011). "Excision repair cross Complementation Group 2(ERCC2), also known as Xeroderma Pigmentosum Complementation Group D (XPD), palys an important role in DNA repair through the nucleotide excision repair pathway." (PMID 40777111, 2025). "The xeroderma pigmentosum complementation group D (XPD) gene, also known as ERCC2, plays important roles in the nucleotide NER pathway." (PMID 35052761, 2021). "Excision repair cross-complimentary group 2 (ERCC2), called xeroderma pigmentosum complementation group D (XPD), is involved in the NER pathway." (PMID 27863412, 2016). "Important members of the NER pathway, namely excision-repair-cross-complementing gene 1 and 2 (ERCC1 and ERCC2), the latest also named Xeroderma pigmentosum complementation group D (XPD) exhibit several polymorphic sites." (PMID 16317430, 2006). "Xeroderma pigmentosum complementation group D (XPD) is a UV-sensitive syndrome and a rare incurable genetic disease which is caused by the genetic mutation of the excision repair cross-complementation group 2 gene (ERCC2)." (PMID 33802476, 2021).
melanoma (11 papers, 2010 to 2025). A malignant, usually aggressive tumor composed of atypical, neoplastic melanocytes. "As an Ercc2 knockout is lethal, we first transfected the murine melanoma cell line WT31 with a doxycycline (Dox)-inducible human wild-type ERCC2 (the gene encoding XPD) or R722W." (PMID 40918647, 2025). "In summary, we have successfully applied whole-exome sequencing for an unexplained molecular cause of melanoma for diagnosis of XP and identified a rare ERCC2 missense mutation (c." (PMID 38028607, 2023). "Our findings confirm that the homozygous ERCC2 (p.R683Q) mutation was responsible for causing melanoma and other cancer types in the family." (PMID 38028607, 2023). "Moreover, mutations in ERCC2 were connected with different types of cancer, including melanoma." (PMID 38028607, 2023). "The results for ERCC2 rs50871 was opposite to the previous findings in melanoma or head and neck cancer, in which the GG genotype was related to favorable survival." (PMID 27340861, 2016). "Many studies have examined the association of genetic polymorphisms with melanoma risk; for instance, variants of the DNA repair-related genes XPD/ERCC2 are associated with cutaneous melanoma." (PMID 24281076, 2010). "On the other hand, carriers of the ERCC2 p.R683Q do not have a risk of developing melanoma." (PMID 38028607, 2023). "The top final variants and their corresponding genes most relevant to hereditary cancers and melanoma and present in both the patient and the sibling with a brain tumor, but not in the control, are in WRN, TYRP1, and ERCC2, shown in and discussed as follows." (PMID 38028607, 2023).
esophageal cancer (10 papers, 2012 to 2025). A primary or metastatic malignant neoplasm involving the esophagus. "In the present study, we also found a significant trend for the rs13181 allele T → G effect on ERCC2 transcript expression levels in different ethnic populations, indicating that the ERCC2 rs13181 SNP may be a underlying genetic determinant of esophageal cancer risk." (PMID 25209371, 2014). "In addition, we could not validate the findings of the previously published candidate gene study on ERCC1 (rs11615 and rs3212986), ERCC2 (rs13181 and rs1799793), and SLC22A2 (rs316019) in our head and neck and esophageal cancer discovery cohort." (PMID 34834585, 2021).
prostate carcinoma (10 papers, 2012 to 2022). A carcinoma that arises from epithelial cells of the prostate gland. "Except for one protective variant (MTHFR rs1801133) for prostate cancer (OR = 0.684, 95% c.i.=0.565–0.828), six of the seven variant (in MGMT, XRCC1, OGG1, ERCC2 and CASC8) showed risks for prostate cancer." (PMID 26967244, 2016).
urothelial carcinoma (9 papers, 2015 to 2025). A malignant neoplasm derived from the transitional epithelium of the urinary tract (urinary bladder, ureter, urethra, or renal pelvis). "Polymorphisms in various DDR genes such as ERCC2 have previously been associated with the development of urothelial carcinoma." (PMID 35419031, 2022). "For ERCC2, evidence is accumulating that somatic mutations are a predictive marker of cisplatin-response in urothelial carcinoma." (PMID 34715822, 2021). "The selection index was clearly above the expected range in carcinomas of the urinary tract, in which 41 samples out of 763 harbored damaging ERCC2 mutations." (PMID 34966786, 2021). "In urothelial carcinoma, we and others recently identified recurrent ERCC2 mutations, and show that ERCC2- deficient tumors have increased response rates to cisplatin- based chemotherapy regimens." (PMID 26909362, 2015). "Remarkably, a high frequency of ERCC2 (32%) mutations was detected as noted recently that have been found to be associated with an improved response to platinum chemotherapy in advanced urothelial carcinoma." (PMID 32445084, 2020). "The ERCC6/CSB 1097Val/Val genotype enhanced susceptibility to advanced (T ≥ 2) urothelial carcinoma, and the ERCC2/XPD 312Asn allele seemed to promote tumor malignancy, since its frequency was increased in patients with T ≥ 2 high grade tumors as compared to T ≥ 2 low grade neoplasms." (PMID 26649138, 2016).
hepatocellular carcinoma (8 papers, 2009 to 2023). A malignant tumor that arises from hepatocytes. "The aim of this meta-analysis was to assess the prognostic value of XRCC1, XRCC3, and ERCC2 gene polymorphism in hepatocellular carcinoma (HCC)." (PMID 31281357, 2019).